FN1 (fibronectin 1)
Diseases named in the same sentence as FN1 in open-access papers (continued):
Sharing a sentence is not in itself a finding about the gene and the disease.
ovarian carcinoma (continued). "In our paper, we compared two different ovarian cancer cell lines with different migration and invasion abilities and found a new protein marker, FN1, which seems to be a strong candidate marker for the diagnosis of aggressive ovarian cancer." (PMID 34093898, 2021). "We have also previously shown that FN1 (evaluated by IHC) is an independent prognostic factor for ovarian cancer patients." (PMID 32961775, 2020). "In the present study we identified TGFBI, TNC, and FN1 as potential mediators of TAM-induced ovarian cancer migration, underscoring the known role of ECM proteins in tumor progression." (PMID 32312959, 2020). "In vivo, ovarian cancer cells displayed decreased proliferation and metastasis in mice bearing a tissue-specific deletion of Fn1 in the lining of the peritoneal cavity." (PMID 32426283, 2020). "Accordingly, the highest FN1 expression is observed in the mesenchymal subtype of ovarian cancer which is characterized by the worst prognosis." (PMID 31936272, 2020). "Kenny and colleagues proceeded to show that ovarian cancer cells recruit HPMCs to establish metastatic colonies by inducing an upregulation in the levels of fibronectin 1 (FN1) mRNA and protein in HPMCs which promote cell adhesion." (PMID 30096959, 2018). "The involvement of matrix deposition in the in vivo homing/adhesion of ovarian cancer cells in the peritoneum has been elegantly demonstrated by other Authors using either floxed fn1 mice or a function-blocking α5β1-integrin antibody." (PMID 26625210, 2016). "Other genes linked to ovarian cancer were also identified as TAF4B targets in TAF4B-overexpressing SIGCs, including c-Jun, matrix metalloproteinase-3 (Mmp-3), and Fibronectin-1 (Fn1)." (PMID 24653979, 2014). "Importantly, high expression levels of FN1 and ITGB1 are linked with poorer survival in ovarian cancer patients, highlighting the potential clinical importance of this signaling axis." (PMID 40862729, 2025). "Meanwhile, this study provided new insights into the heterogeneity of tumor cells and suggested a potential therapeutic target, FN1, which could be helpful for precise immunotherapy of ovarian cancer." (PMID 40612060, 2025). "The survival curves for the two groups exhibited significant differences, suggesting that FN1 could serve as a valuable prognostic indicator for ovarian cancer." (PMID 40612060, 2025). "Examining the role of C3 FN1+ TCs in the malignant proliferation of TCs within omental tissue, leading to carcinogenesis, might provide new insights for targeted therapies in ovarian cancer." (PMID 40612060, 2025). "Patient stratification could be reliably achieved through the utilization of FN1, which might serve as a prognostic biomarker for ovarian cancer." (PMID 40612060, 2025). "Notably, FN1 is a potential biomarker for the diagnosis of ovarian cancer, bladder cancer, and glioblastoma." (PMID 38825675, 2024). "In addition, FN1 is involved in the development of multiple cancers, including CC, oral squamous cell carcinoma, nasopharyngeal carcinoma, ovarian cancer, renal cancer, and thyroid cancer." (PMID 36880057, 2023). "FN1 was an independent prognostic factor in the overall survival of ovarian cancer patients." (PMID 35370699, 2022). "FN1 promotes ovarian cancer metastasis by activating the PI3K/Akt pathway." (PMID 36171259, 2022). "FN1 was found to be extremely upregulated in human ovarian cancer and colorectal cancer models." (PMID 36081567, 2022). "In addition to MYC, CDC37, and FN1, we discovered that celastrol regulated inflammatory pathways in ovarian cancer." (PMID 35370699, 2022). "In ovarian cancer, FN1 induces invasion and migration by upregulating the PI3K/Akt pathway." (PMID 35370699, 2022).
ovarian carcinoma (continued). "HGSOC, the most common and lethal form of ovarian cancer, Upregulation of FAP was found in advanced stage HGSOC patients, showing association with poor prognosis via FN1 pathway, the association of FAP network shows FN1 can be a potential downstream gene leading to HGSOC survival." (PMID 35057823, 2022). "FN1, involved in cell adhesion and migration processes, has been reported to be crucial in tumor progression and as a potential biomarker in multiple cancers including colorectal cancer, gastric cancer, ovarian cancer, and prostate cancer." (PMID 35615147, 2022). "In conclusion, based on in vitro experiment results and the results from the online database analysis, we believe that FN1 could be used as a marker of ovarian cancer detection and could also be used as a progress indicator for ovarian cancer patients." (PMID 34093898, 2021). "Both of the results indicated FN1 should be a good marker for ovarian cancer patients." (PMID 34093898, 2021). "It was suggested that FN1 could be used as a marker to indicate tumor progression in ovarian cancer." (PMID 34093898, 2021). "Taken together, our results indicated that FN1 could be used as a marker for aggressive ovarian cancer detection and can also be applied as an indicator of poor progression for the patients." (PMID 34093898, 2021). "In ovarian cancer, FOXM1 also induces the expression of integrins and matrix proteins: ITGB1, ITGAV, ITGA5, LMNB1, and FN1, which may facilitate adhesion of ovarian cancer cells to new organs." (PMID 34205406, 2021). "Based on these results, we believe that FN1 could be involved in the progression of ovarian cancer and could be the main reason for the differences in the migration and invasion abilities of these two cell lines." (PMID 34093898, 2021). "In addition, the expression of ZIP13 in the ovarian cancer samples was positively correlated with those pro-metastasis genes, such as Snail, Slug, FN1, and was negatively correlated with that tumor suppressor CDH1 (E-cad) gene." (PMID 34154618, 2021). "In this context, FN1 has been proposed as a promoter of ovarian cancer released by CAFs45 and TAMs27, a hypothesis our results confirm." (PMID 32312959, 2020). "FN1 is demonstrated to over-express in ovarian cancer, which could eventually influence the formation of multicellular aggregate of ovarian cancer cells, migration and invasion of cancer cells, and aggravating platinum-resistance to deactivate chemotherapy." (PMID 33109151, 2020). "Additionally, epithelial-mesenchymal transition of ovarian cancer is shown to relate to aberrant expression of FN1." (PMID 33109151, 2020). "Thus, we inferred that celastrol could inhibit the invasion and migration of ovarian cancer by downregulating the expression of FN1." (PMID 35370699, 2022). "Celastrol might modulate the PI3K/Akt pathway in ovarian cancer by interacting with FN1." (PMID 35370699, 2022). "FN1 could also potentially be applied as an indicator of ovarian cancer progression or metastasis." (PMID 34093898, 2021). "FN1 could be a new biomarker for ovarian cancer detection and progress indicator." (PMID 34093898, 2021). "Therefore, FN1 and its regulatory factors, including genes, non-coding RNAs and epigenetic regulations, might be valuable candidates for ovarian cancer studies." (PMID 33109151, 2020). "According to a literature at ovarian cancer, which demonstrated that mesothelial cells experiencing EMT process and expressing higher level of FN1, inducing the activation of AKT pathway in cancer cells." (PMID 39968688, 2025). "The prognostic role of COL1A1, FN1, EDN1 (ET-1) and ARRB1 (β-arr1) gene expression was evaluated using the Kaplan–Meier plotter database and clinical ovarian cancer tissue samples." (PMID 39985042, 2025).
ovarian carcinoma (continued). "We cultured HOFs until they reached confluence and examined the impact of ET-1, a soluble mediator, on the expression of key ECM proteins in ovarian cancer, specifically collagen type I alpha 1 chain (COL1A1) and FN1, both of which are express by HOFs." (PMID 39985042, 2025). "DAB2 expression had significant positive correlations with mesenchymal markers (ZEB2, TGFβ1, SNAI2, ZEB1, FN1, MMP2, TWIST1 and MMP3) and CSC markers (CD44 and MYD88) in ovarian cancer cell lines (CCLE) and tissues (TCGA: RNA sequencing and microarray)." (PMID 37815603, 2023). "Therefore, celastrol might modulate the PI3K/Akt pathway in ovarian cancer by interacting with FN1." (PMID 35370699, 2022). "In ovarian cancer, c-MYC, CDC37, and FN1 play essential roles in the initiation and progress of ovarian cancer." (PMID 35370699, 2022). "Peritoneal dissemination of ovarian cancer induces intercellular interactions through the FN1/AKT signaling pathway and induces the reduction in platinum sensitivity in ovarian cancer cells." (PMID 34567847, 2021). "Re-expression of miRNAs of the miR-200 family reduced expression of its target genes, including ZEB1, ZEB2, FN1 and class III β-tubulin (TUBB3), and inhibited ovarian cancer cell migration and invasion." (PMID 28399108, 2017). "In this module, 5 genes (FN1, MMP2, MMP1, PLAU, and SPARC), colored in green, were identified as ovarian cancer-related genes in the DDOC database." (PMID 25611546, 2015). "FN1 and CLSTN1 were also reported in another study as being differentially spliced in breast and ovarian cancer versus normal tissue." (PMID 21118496, 2010). "Notably, FN1 and EFEMP1, two critical ECM regulators, were under expressed in ovarian cancer relative to the controls, supporting their role in impaired adhesion and aggressive tumor phenotypes." (PMID 41228302, 2025). "These pathways could represent central nodes that reconcile the seemingly discordant regulation of FN-1 and CXCL8 between different ovarian cancer cell lines." (PMID 41382114, 2025). "From the total of 34 ligand and receptor genes identified in these interactions, seven (COL1A1, ITGB5, COL1A2, FGFR2, FN1, IGF1, and IGF2) were consistently up-regulated and predicted worse overall survival in two additional cohorts (TCGA and GSE9891) of ovarian cancer patients." (PMID 36352420, 2022). "However, the biological function of FAM48B1 is rather unclear, and FN1 has been quite well characterized, so we decided to focus on evaluating the role of POSTN in ovarian cancer progression and metastasis." (PMID 36550569, 2022). "These alterations were shown to facilitate the adhesion of ovarian cancer cells mainly via (i) exposure of submesothelial ECM, where cancer cells preferably adhere, and via (ii) upregulated expression of ICAM-1/VCAM-1, HA, and FN1, providing integrin- and CD44-mediated ovarian cancer cell adhesion." (PMID 33270665, 2020). "Several genes found in our analysis have previously been described as biomarkers of ovarian cancer or potential therapeutic targets, including genes from the ITGA and ITGB superfamily, laminins, fibroblast growth factors, collagens, insulin growth factors, EGFR, FN1, EPHA2, TNC, SPP1, and VTN." (PMID 36352420, 2022). "On the other hand, FN1 might also constitute an extracellular substrate for ovarian cancer cell aggregation in spheroids in the absence of stromal fibroblasts." (PMID 35055018, 2022). "Chao and his colleagues reported that LMX1A could inhibit the EMT pathway by upregulating the epithelial marker CDH1 and downregulating the mesenchymal markers CDH2 and FN1 by repressing the EMT-related transcription factors SNAIL, SLUG, and SIP1 in ovarian cancer." (PMID 32751497, 2020).
ovarian carcinoma (continued). "In addition, the stimulation with exogenous TGF-β1 promoted FN1 gene transcription and effectively rescued the lack of production of endogenous FN protein in RSK1/RSK2 silenced ovarian cancer cells." (PMID 26625210, 2016).
gastric cancer (80 papers, 2007 to 2025). A primary or metastatic malignant neoplasm involving the stomach. "For example, a high expression level of fibronectin 1 (FN1) is associated with poor prognosis in gastric cancer." (PMID 38054018, 2023). "We found that poor prognosis was associated with high expressions of PLAU1 and FN1 on ovarian, lung and gastric cancers." (PMID 31443700, 2019). "Fendrr downregulation is associated with poor prognosis in gastric cancer due to its downregulating on fibronectin 1 expression." (PMID 29416790, 2018). "FN1 has been implicated in invasion and metastasis in diverse cancer; however, its role in gastric cancer is less well studied.." (PMID 25167886, 2014). "In gastric cancer, high expression of FN1 is associated with reduced overall survival (OS)." (PMID 38063927, 2023). "Furthermore, it has been reported that in the osteosarcoma cells, COL1A1 and FN1 could be associated with gastric cancer prognosis." (PMID 35578666, 2022). "Also, FN1 could encode fibronectin, which was associated with various cancers precession, including cervical cancer, gastric cancer, colorectal cancer." (PMID 32714651, 2020). "Overexpression of FN1 promoted gastric cancer migration, invasion, EMT, and metastasis via RAP1B in vitro and in vivo." (PMID 40638546, 2025). "Fn1 and JamL serve as prognostic biomarkers for breast and thyroid cancers, lung adenocarcinoma, and gastric cancer, while Ddit4 is a potential prognostic biomarker for colorectal cancer 27-32." (PMID 40206211, 2025). "Research indicates that FN1 significantly promotes the invasive and metastatic abilities of gastric cancer cells." (PMID 40642086, 2025). "Among the enriched pathways related to poor prognosis, five theranostic markers of interest were identified as deregulated and enriched in gastric cancer, including vWF, FN1, THBS1, PCDH7, and F5." (PMID 39456895, 2024). "We identified several genes, including FN1, COL1A2, THBS2, COL3A1, COL5A1, and BGN, which appear to be associated with poorer outcomes for stomach cancer patients." (PMID 38610959, 2024). "AAT acts on FN1 through Snail in colon and gastric cancer, resulting in epithelial-mesenchymal transformation, in turn, promoting cancer progression and metastasis." (PMID 36712921, 2023). "In this study, we found that c-Myc directly facilitated the transcription of GALNT6 and MGAT1 in gastric cancer cells, leading to O-glycosylation or N-glycosylation and stabilization of FN1 and GLUT1 protein, respectively." (PMID 37993881, 2023). "GRg3 downregulates NRP1 expression, blocks the interaction between NRP1 and FN1, and inhibits the malignant progression of gastric cancer MGC-803/MKN-28." (PMID 36313365, 2022). "In gastric cancer, FENDRR inhibits cell invasion and migration by downregulating fibronectin 1, and its low expression is associated with poor prognosis." (PMID 35928921, 2022). "High expression of COL1A1, COL3A1, COL5A1, FN1, and SPARC was significantly associated with poor survival in gastric cancer patients (p < 0.05)." (PMID 35739492, 2022). "In a mouse model, inhibition of miR-1278 increased fibronectin 1 expression and promoted gastric cancer progression." (PMID 35741311, 2022). "NRP1 interacts with fibrillin-1 (FN1) to promote the malignant progression of gastric cancer cells by affecting cell survival and migration through ECM remodeling." (PMID 36313365, 2022). "FN1 has been recognized to support cell proliferation and migration in multiple tumor types such as gastric cancer, colorectal cancer, thyroid cancer and esophageal squamous cell carcinoma." (PMID 34680394, 2021). "Studies had shown that inhibition of the expression of FN1 can inhibit the invasion and migration of gastric cancer cells." (PMID 33015179, 2020). "Some researchers indicated that FN1 participates in regulating many types of cancer progression, such as gastric cancer, skin squamous cell carcinoma, and papillary thyroid carcinoma." (PMID 32766727, 2020).
gastric cancer (continued). "In gastric cancer tissue, FN1 expression was found to be upregulated and related to invasion and migration." (PMID 29484116, 2018). "FENDER overexpression suppressed invasion and migration by gastric cancer cells in vitro, by downregulating FN1 and MMP2/MMP9 expression." (PMID 25167886, 2014). "Western blot and qRT-PCR analyses showed that transfection of gastric cancer cells effectively inhibited approximately 85% of FN1 expression at the mRNA level and 60% at the protein level, as compared to the expression in the control groups." (PMID 25167886, 2014). "Further analysis revealed that of FENDRR expression is inversely correlated with FN1 mRNA and protein levels in gastric cancer." (PMID 25167886, 2014). "The expression of a subset of these genes—i.e., IL-8, IL-6, and FN-1—along with that of P-p65 was correlated with TP immunoreactivity in gastric cancer tissues." (PMID 25350954, 2014). "Genes associated with lymph node metastasis in human gastric cancer (e.g., Rbp4, Igf2, Fn1) are not significantly upregulated in rats, indicating a lower potential for lymph node metastasis in MNNG-induced rat gastric cancer." (PMID 41211438, 2025). "Evidence suggests that FN1 positively regulates the proliferation and migration of a variety of cancer cells and has been identified as a biomarker for a number of cancers, including gastric cancer and cervical cancer." (PMID 41181151, 2025). "FN1 was shown to promote cell proliferation and migration in stomach cancer cell lines." (PMID 39769169, 2024). "Gastric cancer patients with high expression levels of FN1 (HR = 1.54, P < 0.05), MAC25 (HR = 1.48, P < 0.05), THBS2 (HR = 1.55, P < 0.05), VCAN (HR = 1.32, P = 0.0031), SPARC (HR = 1.42, P < 0.05), MSLN (HR = 1.28, P = 0.0066), and FGA (HR = 1.37, P < 0.05) had shorter survival time." (PMID 36842141, 2023). "FN1 plays a critical role in the development of ovarian, thyroid, renal, cervical, breast, and gastric cancers." (PMID 36081907, 2022). "FN1 overexpression also accelerated the migration and invasion of gastric cancer." (PMID 36035176, 2022). "FN1 is able to promote cell proliferation and migration in gastric cancer cell lines." (PMID 35252204, 2022). "In addition, internalization of gastric cancer TDEs upregulates expression of adhesion-related molecules, including fibronectin-1 and laminin-γ1, in PMCs and promotes PMC-gastric cancer cell adhesion, which favors tumor settlement." (PMID 34109113, 2021). "Moreover, circ-AKT3, circ_0081143, and circ-FN1 were documented to enhance CDDP resistance of human gastric cancer cells." (PMID 32855967, 2020). "Interestingly, FN1 was reported to be elevated in omental-derived mesothelial cells treated with cancer exosomes during the development of peritoneal metastasis of gastric cancer." (PMID 31803630, 2019). "Silencing FENDRR increases FN1 expression in gastric cancer cells and increases their migration." (PMID 29641489, 2018). "In this study, a total of 971 DEGs and 15 hub genes were selected, and BGN, MMP2, COL1A1 and FN1 might be the core genes of gastric cancer." (PMID 29050278, 2017). "It was found that expression of BGN (HR 1.9 [1.56–2.32], P = 1.3 × 10–10) was associated with worse overall survival (OS) for gastric cancer patients, as well as MMP2 (HR 1.78 [1.47–2.16], P = 2.6 × 10–9), COL1A1 (HR 1.49 [1.22–1.81], P = 8.2 × 10–5) and FN1 (HR 1.46 1.23–1.74], P = 1.3 × 10–5)." (PMID 29050278, 2017). "In addition, in gastric cancer tissue samples, the expression of the NFκB-regulated genes, including IL-8, IL-6, and fibronectin-1 was positively correlated with TP expression." (PMID 25350954, 2014). "Moreover, upregulation of FENDRR has the effect of suppressing gastric cancer cell migration and invasion in vitro by targeting FN1 and MMP2/MMP9." (PMID 25167886, 2014). "Of these, IL-8, IL-6, and FN-1 levels were correlated with TP expression in gastric cancer tissues." (PMID 25350954, 2014).